TESK1 (testis associated actin remodelling kinase 1)
Description:
Dual specificity protein kinase activity catalyzing autophosphorylation and phosphorylation of exogenous substrates on both serine/threonine and tyrosine residues (By similarity). Regulates the cellular cytoskeleton by enhancing actin stress fiber formation via phosphorylation of cofilin and by preventing microtubule breakdown via inhibition of TAOK1/MARKK kinase activity (By similarity). Inhibits podocyte motility via regulation of actin cytoskeletal dynamics and phosphorylation of CFL1 (By similarity). Positively regulates integrin-mediated cell spreading, via phosphorylation of cofilin. Suppresses ciliogenesis via multiple pathways; phosphorylation of CFL1, suppression of ciliary vesicle directional trafficking to the ciliary base, and by facilitating YAP1 nuclear localization where it acts as a transcriptional corepressor of the TEAD4 target genes AURKA and PLK1. Probably plays a central role at and after the meiotic phase of spermatogenesis (By similarity).
Tractability: Small molecule: a high-quality ligand is known; it belongs to a druggable protein family. PROTAC: ubiquitination databases record sites on it; its protein half-life has been measured; a small molecule that binds it is known.
Target class: TKL protein kinase LISK family; Kinase; TKL protein kinase TESK subfamily; Enzyme; Protein Kinase; TKL protein kinase group
Gene: Protein-coding gene on chromosome 9 (35,605,262 to 35,610,041, forward strand). Ensembl gene ENSG00000107140.
Subcellular location: Cytoplasm; Cytoplasm, perinuclear region; Cytoplasm, cytoskeleton, microtubule organizing center, centrosome; Cell projection, lamellipodium
Pathways (Reactome):
Cell-Cell communication: Regulation of cytoskeletal remodeling and cell spreading by IPP complex components
Gene Ontology:
Molecular function: protein binding; protein kinase activity; protein serine/threonine kinase activity; protein serine/threonine kinase inhibitor activity; ATP binding; protein kinase binding; protein serine kinase activity; protein serine/threonine/tyrosine kinase activity; protein tyrosine kinase activity
Biological process: establishment of vesicle localization; negative regulation of cilium assembly; positive regulation of protein localization to nucleus; positive regulation of substrate adhesion-dependent cell spreading; actin cytoskeleton organization; nuclear-transcribed mRNA catabolic process, no-go decay; podocyte cell migration; positive regulation of stress fiber assembly; regulation of actin cytoskeleton organization; regulation of protein localization; spermatogenesis
Cellular component: centrosome; cytoplasm; cytoplasmic vesicle; cytosol; nucleus; perinuclear region of cytoplasm; lamellipodium
Genetic constraint (gnomAD): Loss-of-function variants: 16 observed, 60.22 expected, observed/expected ratio (o/e) 0.27, 90% interval 0.18 to 0.4. The upper end of that interval is the gene's LOEUF score, 0.4, which puts it in group 1 of 6, group 1 being the genes least tolerant of losing a copy. Missense variants: 705 observed, 820.93 expected, observed/expected ratio (o/e) 0.86, 90% interval 0.81 to 0.91. Synonymous variants: 316 observed, 344.62 expected, observed/expected ratio (o/e) 0.92, 90% interval 0.84 to 1.01.
Homologues: Orthologues: chimpanzee TESK1 (99% identical), macaque TESK1 (99% identical), rabbit TESK1 (96% identical), dog TESK1 (96% identical), guinea pig TESK1 (96% identical), pig TESK1 (96% identical), mouse Tesk1 (93% identical), rat Tesk1 (92% identical), zebrafish tesk1a (50% identical), zebrafish tesk1b (48% identical). Paralogues in human: TESK2 (43% identical), LIMK2 (23% identical), LIMK1 (23% identical), MAP3K9 (22% identical), MAP3K10 (19% identical), MAP3K21 (19% identical), LRRK2 (19% identical), MAP3K11 (18% identical), MAP3K20 (18% identical), TNNI3K (17% identical), BRAF (16% identical), RIPK1 (16% identical), and 11 more.
Diseases named in the same sentence as TESK1 in open-access papers:
TESK1 is named in the same sentence as 10 diseases in open-access papers, as found by Europe PMC text mining. Sharing a sentence is not in itself a finding about the gene and the disease. The quoted sentences say what the papers report.
melanoma (2 papers, 2021). A malignant, usually aggressive tumor composed of atypical, neoplastic melanocytes. "The actin remodelling dynamics of TESK1 confers BRAF inhibitor (PLX4032) resistance to melanoma cells through YAP/TAZ activation." (PMID 33799345, 2021). "Importantly, remodeling of the actin cytoskeleton was demonstrated in BRAFV600E mutant melanoma cells with acquired resistance to BRAF inhibitor vemurafenib, and depletion of TESK1, a kinase that regulates actin cytoskeleton dynamics and reversed resistance to vemurafenib." (PMID 34201061, 2021).
glomerular disease (1 paper, 2018). "While further studies will be necessary to determine the specific role of TESK1 in glomerular disease processes in vivo, these data suggest an important role for TESK1 in modulating cytoskeletal dynamics in glomerular podocytes, which may be directly relevant to glomerular disease processes." (PMID 30115939, 2018). "Thus, TESK1 regulates podocyte cytoskeletal dynamics in glomerular podocytes and may play an important role in regulating glomerular filtration barrier integrity in glomerular disease processes." (PMID 30115939, 2018).
orchitis (1 paper, 2021). Inflammation of one or both testes due to viral or bacterial infections. "This present study reveals that the dyes could impair testicular function as evident in the up-regulation of pro-inflammatory cytokines and down-regulation of TESK-1 gene expression and architecture of the testes leading to Orchitis." (PMID 33565293, 2021).
Wilms’ tumours (1 paper, 2021). "High TESK1 protein expression is characterized in Wilms’ tumours (WTs) and could be essential for WT onset." (PMID 33799345, 2021).
cancer (3 papers, 2015 to 2024). A tumor composed of atypical neoplastic, often pleomorphic cells that invade other tissues. "While KIT mutations are well-known drivers of GIST, tissue-specific genes such as the serine/threonine protein kinase TESK1, the myelin regulatory factor MYRF, as well as the 5-oxo-L-prolinase OPLAH or the zinc influx transporter SLC39A9 have not been associated with cancer before." (PMID 26102504, 2015).
TESK1 also shares sentences with these, for which no sentence is quoted: bone marrow failure (1 paper); chromosomal instability syndrome (1); colon cancer (1); Fanconi anemia complementation group G (1); osteosarcoma (1).